KRT38 (keratin 38)
Synonyms: HHA8; KRTHA8; HA8
Tractability: No criterion of Open Targets' tractability assessment is met for any kind of drug.
Gene: Protein-coding gene on chromosome 17 (41,436,154 to 41,440,983, reverse strand). Ensembl gene ENSG00000171360.
Pathways (Reactome):
Developmental Biology: Formation of the cornified envelope; Keratinization
Gene Ontology:
Molecular function: protein binding; structural constituent of skin epidermis; structural molecule activity
Biological process: epithelial cell differentiation; intermediate filament organization; morphogenesis of an epithelium
Cellular component: extracellular exosome; cytoskeleton; cytosol; keratin filament
Genetic constraint (gnomAD): Loss-of-function variants: 47 observed, 43.94 expected, observed/expected ratio (o/e) 1.07, 90% interval 0.85 to 1.36. The upper end of that interval is the gene's LOEUF score, 1.36, which puts it in group 5 of 6, group 1 being the genes least tolerant of losing a copy. Missense variants: 627 observed, 585.54 expected, observed/expected ratio (o/e) 1.07, 90% interval 1 to 1.14. Synonymous variants: 258 observed, 241.83 expected, observed/expected ratio (o/e) 1.07, 90% interval 0.96 to 1.18.
Homologues: Orthologues: chimpanzee KRT38 (99% identical), macaque KRT38 (96% identical), dog KRT38 (76% identical), dog KRT37 (74% identical). Paralogues in human: KRT37 (90% identical), KRT31 (55% identical), KRT32 (55% identical), KRT35 (54% identical), KRT33A (54% identical), KRT33B (53% identical), KRT36 (53% identical), KRT34 (52% identical), KRT40 (47% identical), KRT39 (47% identical), KRT14 (40% identical), KRT15 (39% identical), and 56 more.
Diseases named in the same sentence as KRT38 in open-access papers:
KRT38 is named in the same sentence as 3 diseases in open-access papers, as found by Europe PMC text mining. Sharing a sentence is not in itself a finding about the gene and the disease. The quoted sentences say what the papers report.
staphylococcus aureus infection (1 paper, 2023). An infectious process in which the bacteria Staphylococcus aureus is present. "KEGG pathway: The bar chart of the KEGG pathways related to the set of genes showed that most genes were involved in Staphylococcus aureus infection (KRT32, C3, KRT38, and KRT37) and the estrogen signaling pathway (KRT32, KRT38, and KRT37)." (PMID 37900279, 2023).
cancer (1 paper, 2023). A tumor composed of atypical neoplastic, often pleomorphic cells that invade other tissues. "In addition, the pharmacogenomic study of the DEPs in GSCA also showed that the downregulation of proteins such as PRDX4, GDI1, and YWHAE and the upregulation of proteins such as CLEC3B, KRT38, KRT37, and HNRNPCL1 were linked to higher sensitivity toward 30 pan-cancer CTRP drugs." (PMID 37900279, 2023).
tumor (1 paper, 2025). "The four most significantly downregulated genes in COM, compared to healthy tissue controls, were all keratin genes (KRT33A, KRT86, KRT34, and KRT38), which is consistent with a potential loss of epithelial differentiation, a hallmark of aggressive tumor behavior." (PMID 40647405, 2025).